TMEM225 (transmembrane protein 225)
Description:
Probably inhibits protein phosphatase 1 (PP1) in sperm via binding to catalytic subunit PPP1CC.
Synonyms: PMP22CD; PPP1R154; SPATA47
Tractability: Antibody: UniProt predicts a signal peptide or a membrane-spanning region.
Gene: Protein-coding gene on chromosome 11 (123,882,920 to 123,885,670, reverse strand). Ensembl gene ENSG00000204300.
Subcellular location: Cytoplasmic vesicle, secretory vesicle, acrosome membrane
Gene Ontology:
Cellular component: acrosomal membrane
Genetic constraint (gnomAD): Loss-of-function variants: 10 observed, 17.94 expected, observed/expected ratio (o/e) 0.56, 90% interval 0.34 to 0.94. The upper end of that interval is the gene's LOEUF score, 0.94, which puts it in group 4 of 6, group 1 being the genes least tolerant of losing a copy. Missense variants: 245 observed, 282.21 expected, observed/expected ratio (o/e) 0.87, 90% interval 0.78 to 0.96. Synonymous variants: 101 observed, 98.86 expected, observed/expected ratio (o/e) 1.02, 90% interval 0.87 to 1.21.
Homologues: Orthologues: chimpanzee TMEM225 (95% identical), macaque TMEM225 (85% identical), dog TMEM225 (55% identical), mouse Tmem225 (45% identical), rat Tmem225 (44% identical).
Diseases named in the same sentence as TMEM225 in open-access papers:
TMEM225 is named in the same sentence as 3 diseases in open-access papers, as found by Europe PMC text mining. Sharing a sentence is not in itself a finding about the gene and the disease. The quoted sentences say what the papers report.
asthenospermia (2 papers, 2024 to 2025). "To verify the molecular mechanism of TMEM225 KO-induced asthenospermia in mice, we isolated sperm from the cauda epididymis of 2-month-old mice for label-free quantitative proteome analysis." (PMID 38246484, 2024). "•TMEM225-null mice develop asthenospermia and are infertile." (PMID 38246484, 2024). "In conclusion, our results demonstrate that Tmem225 deletion does not affect spermatogenesis but causes asthenospermia and leads to infertility in male mice through changes in the proteins in epididymal sperm." (PMID 38246484, 2024). "Male Tmem225 KO mice were infertile and SPZ lacking TMEM225 exhibited mitochondrial dysfunction, impaired glycolysis, high ROS levels, reduced motility, and flagellar folding, leading to typical asthenospermia." (PMID 40710375, 2025). "Our study revealed that the absence of TMEM225, a membrane protein expressed solely during spermiogenesis, can lead to the development of classic asthenospermia in mice." (PMID 38246484, 2024).
Azoospermia (1 paper, 2024). Absence of any measurable level of sperm,whereby spermatozoa cannot be observed even after centrifugation of the semen pellet. "Previous studies have found abnormal transmembrane protein 225 (TMEM225) expression levels in patients with nonobstructive azoospermia." (PMID 38246484, 2024). "Previous research revealed abnormal protein levels of transmembrane protein 225 (TMEM225) in infertile male patients with nonobstructive azoospermia." (PMID 38246484, 2024). "Abnormal levels of transmembrane protein 225 (TMEM225), a testis-specific protein, have been found in patients with nonobstructive azoospermia, suggesting that TMEM225 plays an essential role in male fertility." (PMID 38246484, 2024).
Infertility (1 paper, 2024). "Specifically, TMEM225-deficient mice were infertile, and sperm collected from the cauda epididymis exhibited significantly reduced viability, varying degrees of tail folding, and high ROS levels." (PMID 38246484, 2024). "Furthermore, the expression of GAPDHS, which was downregulated in sperm with Tmem225 deletion, resulted in reduced sperm motility and infertility in mice." (PMID 38246484, 2024). "Therefore, we investigated the mechanisms responsible for infertility in male mice after Tmem225 deletion." (PMID 38246484, 2024).